TSPO (translocator protein)
Diseases named in the same sentence as TSPO in open-access papers (continued):
Sharing a sentence is not in itself a finding about the gene and the disease.
tumor (continued). "Grade I tumors showed a mean TSPO expression of 6.99 in tumor tissues compared to 5.55 in non‐tumor tissues." (PMID 40550494, 2025). "The mean TSPO gene expression in male patients was 9.39 in tumor tissues and 7.58 in non‐tumor tissues." (PMID 40550494, 2025). "The mean TSPO expression in female patients was 11.10 in tumor tissues and 7.39 in non‐tumor tissues." (PMID 40550494, 2025). "Similar to the study's conclusion that TSPO gene expression increases with tumor malignancy, our research also identified elevated TSPO levels in more advanced CRC grades." (PMID 40550494, 2025). "Patients aged 50 and above had mean TSPO expression levels of 10.35 in tumor tissues and 7.34 in non‐tumor tissues." (PMID 40550494, 2025). "Grade III tumors displayed significantly higher TSPO expression, with a mean of 16.86 in tumor tissues and 10.89 in non‐tumor tissues." (PMID 40550494, 2025). "In the C6 glioma rat model, ScBsAbsAng-2/TSPO reduced endothelial co-expression of Ang-2/TSPO and increased tumor-cell apoptosis by 3.2-fold." (PMID 41209565, 2025). "Similar to the human brain, TSPO-PET signals of the tumor correlated with contralateral PET signal enhancement in a voxel-wise analysis." (PMID 39150564, 2024). "TSPO, which was directly linked to GPX4-driven ferroptosis in the murine model, was highly upregulated in quiescent tumor cell populations." (PMID 39192032, 2024). "We studied dependencies of contralateral TSPO expression from tumor characteristics such as localization, biological tumor volume, and TSPO-PET signal magnitude." (PMID 39150564, 2024). "A previous study found that TSPO levels correlated to increased tumor invasion levels using immunohistochemistry and real-time PCR." (PMID 38585455, 2024). "Due to its overexpression in tumor lesions, TSPO offers diverse applications in pharmacological studies, specifically in the field of oncology and nuclear medicine." (PMID 38585455, 2024). "The abundance of TSPO in cancer cells has been used in positron emission tomography (PET)-imaging with TSPO-specific ligands to detect tumor cells." (PMID 38675106, 2024). "To minimize this potential impact of tumor cell invasion on TSPO expression, we focused on the contralateral hemisphere and used only tumors without bilateral manifestation." (PMID 39150564, 2024). "Tissue-based analyses in tumor-free sham-injected mice revealed a shift over time in the contribution to the overall TSPO signal from mainly microglia/macrophage activation at early time points to astrogliosis at late time points after penetrating TBI." (PMID 38255293, 2024). "In this regard, our data also indicate associations of distant neuroinflammation with poor prognosis even independently from the tumor TSPO expression." (PMID 39150564, 2024). "As shown in the present study, astrocytes can be a relevant additional source of TSPO expression contributing to the TSPO radioligand uptake at tumor edges." (PMID 38255293, 2024). "Cellular tracer uptake measures identified significantly higher TSPO tracer uptake in myeloid cells of the contralateral hemispheres of SB28 tumor mice compared to sham mice (2.8-fold, P < 0.0001) and healthy control mice (4.2-fold, P < 0.0001)." (PMID 39150564, 2024). "For example, progress has been made to detect and monitor CD11b, a tumor-associated myeloid marker, CD206, which is highly expressed in M2 macrophages, and TSPO, a mitochondrial receptor upregulated in activated macrophages via novel PET imaging agents." (PMID 39104861, 2024). "The overall correlation of all 123 sub-regions between both hemispheres already indicated regional dependency of contralateral TSPO-PET signal elevations from the particular tumor localization (R = 0.488, P < 0.0001)." (PMID 39150564, 2024). "The results showed that TSPO knockdown significantly suppressed tumor growth and facilitated T‐cell infiltration." (PMID 36994647, 2023).
tumor (continued). "Apart from SUVmax on TSPO PET, parameters associated with survival were age, MGMT promoter methylation status, and T2-weighted MRI tumor volume." (PMID 37536737, 2023). "Most interestingly, tumor volumes drawn on TSPO PET were greater, with only a moderate correlation of the “hot spots”, than those delineated on amino-acid PET." (PMID 37238297, 2023). "Coculture of BTICs with tumor reactive cytotoxic T cells or with T cell-derived factors induced TSPO up-regulation through T cell derived TNFα and IFNγ." (PMID 37158962, 2023). "Consistent with the in vitro result, following the knockdown of TSPO, the reduction of tumor burden and lung metastasis were observed, whereas overexpression of TSPO resulted in the opposite outcome." (PMID 36994647, 2023). "TSPO upregulation in the tumor cells required antigen specific activation of T cells interacting with the tumor cells and was initiated through IFNγ and TNFα secreted by activated T cells." (PMID 37158962, 2023). "We also evaluated the prognostic role of TSPO expression in the whole TMA cohort with tumor p16 status." (PMID 38162485, 2023). "Next, we observed comparable upregulation of TSPO expression when we used the culture supernatant of activated FluTC or of activated autologous tumor-infiltrating lymphocytes (TILs) isolated from GB 129 (TIL129) instead of the T cells." (PMID 37158962, 2023). "In all GBM patients, TSPO PET results were positive with high tumor-to-background contrast (median TBRmax = 6.61), while a very low signal was found in the normal brain." (PMID 37238297, 2023). "In silico results also supported this finding showing better patient 3-year OS with high tumor TSPO expression." (PMID 38162485, 2023). "IHC analysis of TMA and subcutaneous xenografts tumor tissues showed that TSPO was positively correlated with P62 and Nrf2." (PMID 36994647, 2023). "To further investigate the role of TSPO on tumor growth and metastatic potential in vivo, we established subcutaneous xenograft tumor and lung metastasis models in nude mice." (PMID 36994647, 2023). "We show that human primary BTICs upregulate TSPO upon contact with tumor antigen reactive cytotoxic T cells." (PMID 37158962, 2023). "The results showed that TSPO protein expression in HCC tissues was higher than that in adjacent non‐tumor tissues (p = 0.002), consistent with the HPA database analysis." (PMID 36994647, 2023). "Tumor volume defined by [18F]FET PET or contrast-enhanced MRI correlated weakly with TSPO tracer uptake." (PMID 36329288, 2023). "After 20 h of co-culture, BTICs upregulated TSPO mRNA and protein where TSPO expression correlated with the applied antigen concentrations, indicating that recognition of the model tumor antigen by T cells was required to induce TSPO." (PMID 37158962, 2023). "After dividing our cohort into site-specific subgroups, we assessed the prognostic value of TSPO in all evaluated tumor sites." (PMID 38162485, 2023). "After the orthotopic implantation of DIPG007 cells (4 weeks post-injection), brain lysates from tumor-inoculated brains present a high ex vivo TSPO expression in the back brain (brain stem and cerebellum) compared with sham rats’ back brains lysates." (PMID 36293329, 2022). "After CSF-1R inhibition, TSPO signal was detectable mostly at the border of the tumor mass, in line with the imaging results, together with a few Iba1+ and TSPO+Iba1+ cells." (PMID 35115369, 2022). "Immunofluorescence confirms that both pro-inflammatory and anti-inflammatory macrophages were observed mainly in the tumor edge, which is the same region that expresses TSPO and shows greater [11C](R)-PK11195 uptake on PET imaging and autoradiography." (PMID 36559209, 2022). "In line with the results obtained after the chronic treatment, fluorescent labeling revealed the presence of TSPO+ and CSF-1R+ immune cells infiltrating the tumor after depletion of microglia cells." (PMID 35115369, 2022).
tumor (continued). "While DIPG007 TSPO expression seems weaker compared with U87 TSPO overexpression in vitro, it appears to be sufficient to differentiate tumor inoculated brain tissue from healthy brain tissue." (PMID 36293329, 2022). "The temporal and spatial variations in M1, M2, and TSPO expression using immunofluorescence markers are consistent with the tumor distribution of [11C](R)-PK11195 observed on our PET imaging and autoradiography." (PMID 36559209, 2022). "The TSPO expression followed the same pattern, being more expressed at the border of the tumor at both time points, demonstrating an apparent decrease from 1 to 2 weeks." (PMID 36559209, 2022). "TSPO-deficient GL261 glioma mouse model showed high glioma proliferation and hypoxia-induced angiogenesis, ultimately showing bigger tumor mass and extensive hemorrhagic areas." (PMID 35804911, 2022). "TSPO expression by neoplastic cells is suggested as a reliable prognostic biomarker as it increases with histological tumor grade." (PMID 36293329, 2022). "In contrast, a significant increase (61 ± 33%) of [18F]DPA-714 uptake was detected by TSPO imaging in specific areas of the tumor." (PMID 33500706, 2021). "Further analyses are needed to discriminate the specific cell populations that express TSPO within the TME, such as perivascular cells and the subpopulations of tumor-associated infiltrating cells." (PMID 33500706, 2021). "We observed a significant increase in TSPO gene expression in GBM compared to that of non-tumor brain tissue (p < 0.001)." (PMID 34572751, 2021). "The different studies, with either (R)-[11C]PK11195 or challengers, reported specific binding of TSPO radioligands by tumour cells thereby pointing to the difficult discrimination between reactive neuroinflammation and tumour development itself." (PMID 34387719, 2021). "TSPO can be useful in differentiating inflammation from tumor which was illustrated through the use of [18F]-DPA-714 in numerous tumor models (A549, HT29, U87MG, INS-1 and 4T1) compared to in a muscular inflammation model." (PMID 33923410, 2021). "Microglia cells and astrocytes localized primarily at the periphery of the tumor in DMSO-treated cells with little co-localization of TSPO and GFAP." (PMID 33500706, 2021). "In order to determine the TSPO-specificity of the tracer uptake we pre-treated tumour bearing mice and cells with the TSPO-selective ligand PK11195." (PMID 33340054, 2021). "Variations in TSPO expression levels have been related to different diseases, from tumor to endocrine and neurological disorders; thus, this receptor has become an appealing subcellular target for the early diagnosis of a disease involving its overexpression." (PMID 34452175, 2021). "Considering that tumor cells also express TSPO, these results have a positive correlation with reduction in tumor volumes, as seen by contrast-enhanced (CE)-MRI which is in line with the decrease of [18F]FET volumes." (PMID 33500706, 2021). "As shown by the unexpected increase of exclusive areas of [18F]DPA-714 uptake, the anti-proliferative effect of TMZ therapy induced an increase in immunoreactivity of TSPO-expressing glial cells surrounding the tumor mass." (PMID 33500706, 2021). "A significant increase in the mRNA TSPO expression in GBM tumor samples was also observed comparing the three different RNA data platforms available from the TCGA-GBM database as well as in the REMBRANDT and Gravendeel independent datasets (p < 0.001)." (PMID 34572751, 2021). "The authors concluded that TSPO-deficiency triggers HIF-1α upregulation, leading to a subsequent increase in key angiogenesis regulators that fueled angiogenesis and a tumor-promoting microenvironment." (PMID 33066460, 2020). "Translocator Protein 18kDa (TSPO) is highly expressed in myeloid cells and tumor cells, while a normal brain shows only a moderate expression." (PMID 31963507, 2020).
tumor (continued). "The highest TSPO intensity was observed in the tumor cells themselves in several human and murine GBM models." (PMID 31963507, 2020). "The Cancer Genome Atlas (TCGA)-data analysis corroborates the upregulation of TSPO in a bigger cohort of GBM patient samples compared to tumor-free brain tissue." (PMID 31963507, 2020). "To further investigate the identity of the cells expressing TSPO in the tumor microenvironment, we performed immunofluorescent co-staining against CD31 and PDGFRB." (PMID 31963507, 2020). "Other than FET-PET, mitochondrial translocator protein (TSPO)-PET can visualize not only a tumor mass, but also microglial activation in TAM and potentially additional inflammatory components of GBM." (PMID 31963507, 2020). "The implantation of these human GSCs produced patient-derived xenografts (PDX) with a high expression of TSPO in the tumor area for the classical human GBM (GBM2), as well as for the proneural human GBM (GBM14 and NCH644)." (PMID 31963507, 2020). "In patient-derived xenograft and transgenic murine GBM models, TSPO is strongly upregulated in the tumor area compared to normal brain regions." (PMID 31963507, 2020). "Non-invasive imaging using 18F DPA-714 to detect translocator protein (TSPO) expressing cells in vivo that are predominantly macrophages showed a significant decrease (p ≤ 0.01) in macrophage infiltration in shMAPK7 tumours." (PMID 32655131, 2020). "In clinical application of patients with chronic TBI or SCI, we believe selection of the timing of the PET scan is essential in diagnosing tumor‐like overgrowth of remnant undifferentiated hiPSC‐NS/PCs by monitoring the changes in the total amount of TSPO." (PMID 31904914, 2020). "Previously, we showed that TSPO deletion in mouse tumor MA-10 Leydig cells led to reduced mitochondrial membrane potential (ΔΨm) and steroid biosynthesis under cAMP stimulation." (PMID 33383772, 2020). "Co-staining with Iba1- and TSPO-antibodies showed that TSPO was also expressed in Iba1-positive microglia/macrophages in the tumor." (PMID 31963507, 2020). "In light of alterations of various important cell cycle regulators and signaling pathways in GBM, it will be interesting to understand the interactions of TSPO with cell cycle checkpoint molecules and tumor suppressors in more detail." (PMID 33066460, 2020). "Little is known about the underlying expression of TSPO and LAT1 in GBM tumor tissue and associated inflammation in the surrounding area." (PMID 31963507, 2020). "To investigate the specificity of TSPO for tumor tissue, we first analyzed patient GBM samples and compared them to those from a normal human brain." (PMID 31963507, 2020). "By immunofluorescent staining against TSPO, the distinction between tumor-free brain and tumor samples became obvious when using murine Gl261, as well as the classical cdkn2aKOEGFRvIII or proneural 53KOPDGFB GSCs." (PMID 31963507, 2020). "Our model extends recent approaches of TSPO radioligand imaging using xenografting of tumour cells into wild-type animals." (PMID 32561881, 2020). "It is thus not readily possible to discern the relative contributions of infiltrating tumour cells from that of reactive glial cells to the total TSPO expression as measured by in vivo TSPO imaging." (PMID 32561881, 2020). "Mean TSPO OD was higher in the growing group (P = 0.100), but this result was not statistically significant due to the presence of one static tumor with high TSPO OD." (PMID 30388263, 2019). "TSPO is also thought to be involved in Parkinson’s and Alzheimer’s diseases, inflammation, and tumour progression." (PMID 30044440, 2018). "Previous studies showed that the expression of TSPO protein correlated positively with tumour malignancy and negatively with patient survival." (PMID 30044440, 2018).
tumor (continued). "The present case is unusual and interesting because TSPO expression was paradoxically lost in the mitochondria of the tumor cells when assessed by immunofluorescence in comparison to the patient's normal adrenal gland." (PMID 29318061, 2017). "In order to assess the expression of TSPO we obtained additional unstained slides from formalin-fixed paraffin-embedded (FFPE) tissue including a representative section of the tumor with adjacent normal adrenal gland (internal control) of the patient." (PMID 29318061, 2017). "We further confirmed this finding by employing Western blot analysis to semiquantify TSPO expression in tumor and normal adrenal cells." (PMID 29318061, 2017). "Nevertheless, in the realm of cancer, several studies have found an increased TSPO protein expression in cancer cell lines and in tumor biopsies of colon, breast, and prostate." (PMID 29318061, 2017). "TSPO is expressed in healthy tissue but overexpressed in multiple cancers possibly facilitating tumor cell selectivity." (PMID 28218708, 2017). "Alternatively, the time–activity curve (TAC) of an unaffected region or tissue can be used as a reference under the general assumption that the tissue selected as reference has very low TSPO expression, while perfusion is similar to tumour tissue." (PMID 27077069, 2016). "TSPO-positive cells were evenly distributed throughout the tumour tissue as well as in its peripheral, infiltrative component as seen by Buck and colleagues in their preclinical model." (PMID 27077069, 2016). "The heterogeneity of cellular distribution of TSPO that is already present in the normal brain (vascular, parenchyma) is compounded in and around tumours by the variability of vascularization, perfusion and cellularity, typical of high-grade gliomas." (PMID 27077069, 2016). "The rhenium-185 and -187 complex 2 exhibited a moderate affinity (Ki = 159.3 ± 8.7 nM) for TSPO, whereas its cytotoxicity evaluated on TSPO-rich tumor cell lines was lower than that observed for the precursor." (PMID 27399688, 2016). "Both studies observed a positive and significant association between TSPO expression, WHO-designated tumour grade and survival." (PMID 27077069, 2016). "As Nrp1-dependent pathways can play a role in the behavior of tumor-associated macrophages in the periphery, we examined the phenotypic state of the GAMs by assessing them for expression of CD86, CD206, and TSPO, which are markers of inflammatory status." (PMID 26755653, 2016). "A displacement study confirmed the specificity of tracer binding on TSPO as about 78% of the activity in the tumor was displaceable by the unlabeled compound." (PMID 25853015, 2015). "While TSPO staining was detected in all tumor specimens, the high grade samples overall showed a much greater presence of TSPO than that of the low." (PMID 26517124, 2015). "Western blotting analyses of tumor tissue extracts compared to spleen extracts (as positive control) show a similar 18-kDa band confirming the presence of TSPO protein in these cell populations." (PMID 25853015, 2015). "Confirming that the [18F]PBR06 signal represented selective uptake of probe by malignant cells, correlative IHC demonstrated strong expression of TSPO within the myelinated fiber tracts and tumor." (PMID 26517124, 2015). "Correlative IHC confirmed robust expression of TSPO in both tumor and the infiltrated fiber tracts of the contralateral hemisphere." (PMID 26517124, 2015). "This approach tests simultaneously for the absence (respectively presence) of several recognition or binding domains that make up the full PBR/TSPO, whereby the PBR/TSPO-expressing tumour serves as an internal positive control within the same animal." (PMID 25406832, 2014). "As predicted from the readable sequences remaining after the deletion of exons 2 and 3, the tissue of Tspo−/− animals cannot express any functional domains of the PBR/TSPO or similar proteins, whereas the Tspo+/+ tumours express the protein as expected." (PMID 25406832, 2014).